ANKRD53 (ankyrin repeat domain 53)
Description:
Required for normal progression through mitosis. Involved in chromosome alignment and cytokinesis via regulation of microtubules polymerization.
Synonyms: FLJ12056; FLJ36160
Tractability: No criterion of Open Targets' tractability assessment is met for any kind of drug.
Gene: Protein-coding gene on chromosome 2 (70,978,380 to 70,985,499, forward strand). Ensembl gene ENSG00000144031.
Subcellular location: Cytoplasm, cytoskeleton, spindle; Cytoplasm, cytoskeleton, spindle pole
Gene Ontology:
Molecular function: protein binding
Biological process: mitotic metaphase chromosome alignment; positive regulation of microtubule polymerization; regulation of mitotic cytokinesis; regulation of mitotic spindle organization
Cellular component: spindle; spindle pole
Genetic constraint (gnomAD): Loss-of-function variants: 28 observed, 27.84 expected, observed/expected ratio (o/e) 1.01, 90% interval 0.74 to 1.38. The upper end of that interval is the gene's LOEUF score, 1.38, which puts it in group 5 of 6, group 1 being the genes least tolerant of losing a copy. Missense variants: 682 observed, 723.68 expected, observed/expected ratio (o/e) 0.94, 90% interval 0.88 to 1. Synonymous variants: 286 observed, 295.44 expected, observed/expected ratio (o/e) 0.97, 90% interval 0.88 to 1.07.
Homologues: Orthologues: chimpanzee ANKRD53 (98% identical), macaque ANKRD53 (92% identical), dog ANKRD53 (60% identical), pig ANKRD53 (59% identical), guinea pig Ankrd53 (55% identical), rabbit ANKRD53 (52% identical), rat Ankrd53 (48% identical), mouse Ankrd53 (48% identical), tropical clawed frog ankrd53 (27% identical), zebrafish ankrd53 (15% identical).
Diseases named in the same sentence as ANKRD53 in open-access papers:
ANKRD53 is named in the same sentence as 5 diseases in open-access papers, as found by Europe PMC text mining. Sharing a sentence is not in itself a finding about the gene and the disease. The quoted sentences say what the papers report.
gastric cancer (1 paper, 2024). A primary or metastatic malignant neoplasm involving the stomach. "Especially how the TGF-β signaling pathway and ANKRD53 interact to regulate mitosis in gastric cancer." (PMID 38801557, 2024). "Therefore, this study analyzed the potential role of ANKRD53 in STAD for the first time to provide new ideas and theoretical basis for gastric cancer." (PMID 38801557, 2024). "Therefore, we speculate that ANKRD53 and TGF-β pathway may interact to regulate gastric cancer cell mitosis, which deserves further investigation in a follow-up study." (PMID 38801557, 2024).
glioma (1 paper, 2025). A benign or malignant brain and spinal cord tumor that arises from glial cells (astrocytes, oligodendrocytes, ependymal cells). "Even though there are no direct signals of ANKRD53 involvement in glioma, its functions in mitotic fidelity position it as a candidate gene in tumor evolution." (PMID 41300918, 2025).
trisomy 16 (1 paper, 2022). "We analyzed the methylation indices of the promoter regions of 5 DMGs (ANKRD53, TRPV6, GATA3-AS1, SCL13A4, and CALCB) in chorionic villi trophoblasts of miscarriages with trisomy 16 and induced abortions with a normal karyotype using targeted bisulfite massive parallel sequencing." (PMID 35064135, 2022).
cancer (3 papers, 2019 to 2024). A tumor composed of atypical neoplastic, often pleomorphic cells that invade other tissues. "Ankyrin repeat domain 53 (ANKRD53) plays an important role in maintaining chromosome integrity and stability, and chromosome instability is associated with cancer." (PMID 38801557, 2024). "We found that ANKRD53 was associated with Calcium, Hedgehog, MAPK, TGF-β signaling pathways, and pathways in cancer." (PMID 38801557, 2024). "Real-time PCR was performed to check the methylation difference of HOXD9, ZNF154, BCL9, TDRD10, and ANKRD53 genes between the cancer cases and controls." (PMID 34452548, 2021). "Thus, the role of ANKRD53 in cancer development through the regulation of CIN was significant for its mechanism." (PMID 38801557, 2024). "We first examined ANKRD53 mRNA expression in the TCGA dataset by pan-cancer analysis." (PMID 38801557, 2024).
tumor (2 papers, 2024 to 2025). "We first examined the relationship between ANKRD53 and immune cell infiltration as well as the tumor microenvironment to investigate the immunological properties of ANKRD53." (PMID 38801557, 2024). "Regarding the tumor microenvironment (TME), significant differences in TME scores were observed in different ANKRD53 expressions between Stromal, Immune, and ESTIMATE scores." (PMID 38801557, 2024).